FOXM1 (forkhead box M1)
Diseases named in the same sentence as FOXM1 in open-access papers (continued):
Sharing a sentence is not in itself a finding about the gene and the disease.
ovarian carcinoma (continued). "To further confirm the selectivity of STL001 toward FOXM1 regulatory pathways we analyzed the differential gene expression shared between STL001 treatment and FOXM1-KD in ovarian cancer (OVCAR-8) cells via full Transcriptome RNA-seq." (PMID 38697979, 2024). "MR can induce autophagy and apoptosis in cervical cancer cells by inhibiting mTOR-S6K1 signaling, also can effectively inhibit ovarian cancer cell migration and reverse cisplatin resistance by inhibiting the expression of FOXM1." (PMID 38895626, 2024). "In conclusion, we demonstrate that ALKBH5 promotes tumour progression by at least partially stabilizing PVT1 and FOXM1 in ovarian cancer." (PMID 38098223, 2024). "In that study, the authors demonstrated that CCNF is transcriptionally activated by FOXM1 in an ovarian cancer cell line." (PMID 38916959, 2024). "Upregulated ALKBH5 demethylated the long noncoding RNA PVT1 and thus stabilized FOXM1, at least partially, in ovarian cancer." (PMID 38098223, 2024). "We discovered that the pro-tumorigenic transcription factor FOXM1 is specifically induced by the microenvironment in ovarian cancer stem cells, through activation of FAK/YAP signaling." (PMID 38806454, 2024). "We did full transcriptome RNA-seq and analyzed the patterns of gene expression by STL001 in esophageal cancer (FLO-1) cells and differential gene expression shared between STL001 treatment and FOXM1-KD in ovarian cancer (OVCAR-8) cells." (PMID 38697979, 2024). "Our findings suggest that domatinostat, which effectively targets the FOXM1–survivin axis required for the viability of ovarian cancer cells, is a promising option for the treatment of ovarian cancer." (PMID 37445993, 2023). "To this end, we knocked down FOXM1 in ovarian cancer cells and examined its impact on survivin expression." (PMID 37445993, 2023). "FOXM1 was suggested to protect ovarian cancer cells from the cytotoxicity of cisplatin; thus, its high expression translates into chemo-resistance." (PMID 38201468, 2023). "Regarding mechanism, miR-532-3p and FOXM1 were involved in circ_0025033-induced PTX resistance in ovarian cancer." (PMID 38152652, 2023). "Domatinostat reduced the protein and mRNA expression of FOXM1 and survivin and also the viability of ovarian cancer cells alone and in combination with cisplatin or paclitaxel at clinically relevant concentrations." (PMID 37445993, 2023). "It would therefore be of interest to examine such newly developed LSD1 inhibitors for their ability to inhibit FOXM1 expression as well as for their anti-cancer activity against ovarian cancer cells in future studies." (PMID 37445993, 2023). "Here in this study, we tested the possibility of domatinostat, a class I-selective HDAC inhibitor in clinical and preclinical stages of development for the treatment of cancer, as an inhibitor of FOXM1 expression in ovarian cancer cells." (PMID 37445993, 2023). "The deregulation of the FOXM1 transcription factor is a key molecular alteration in ovarian cancer, contributing to the development and progression of ovarian cancer via activation of the target genes." (PMID 37445993, 2023). "DLX1 hosts enhanced MYCN binding, predominantly enriched across a DNA stretch of ~1 kb that flanks its TSS and encompasses the core promoter, as well as TFBSs for FOXM1 that were previously characterized in ovarian cancer." (PMID 37835497, 2023). "The involvement of circ_0025033 in regulating PTX resistance via targeting miR-532-3p and FOXM1 has been reported in ovarian cancer." (PMID 38152652, 2023). "In ovarian cancer tissues and tumor cells, there were high expression of circ_0025033 and FOXM1 and lower expression of miR-532-3p." (PMID 38152652, 2023). "Accordingly, PVT1 can function as an oncogenic factor in ovarian cancer cells by regulating the FOXM1 protein level." (PMID 37573419, 2023). "The authors suggest that ZEB1 and FOXM1 are significant in ERBB2 signaling for peritoneal metastasis of ovarian cancer." (PMID 37324014, 2023).
ovarian carcinoma (continued). "CircRNA PVT1 controlled cell invasion and proliferation through targeting FOXM1 expression by sponging miR-149-5p in ovarian cancer." (PMID 38152652, 2023). "As such, FOXM1 is attracting ever-increasing attention as a viable therapeutic target to overcome the aggressive nature of ovarian cancer." (PMID 37445993, 2023). "We investigated in this study the effects of domatinostat, a class I-selective HDAC inhibitor currently in the clinical stage of development as a cancer therapeutic, on the expression of FOXM1 and viability of ovarian cancer cells." (PMID 37445993, 2023). "In ovarian cancer, silencing of circ_0061140 abolished FOXM1-induced metastasis and cell proliferation via sponging miR-370." (PMID 38152652, 2023). "Collectively, the results presented so far in this study suggested that domatinostat reduced the viability of ovarian cancer cells by targeting the FOXM1-survivin axis." (PMID 37445993, 2023). "Then, we demonstrated that exosomes secreted by HO-ADSCs (HO-ADSC exosomes) enhanced ovarian cancer cell function, and further mechanistic studies showed that the FOXM1, Cyclin F, KIF20A, and MAPK signaling pathways were involved in this process." (PMID 36359787, 2022). "In this study, we aimed to explore new structural types of FOXM1 inhibitors utilizing previous binding conformations to identify potential drug candidates for ovarian cancer." (PMID 36505747, 2022). "Studies have shown that FOXM1 expression is increased in cisplatin-resistant cancer tissues, and that FOXM1 promotes the malignant behavior of ovarian cancer and induces cisplatin chemoresistance." (PMID 36505747, 2022). "Combining existing first-line chemotherapy drugs with FOXM1 prolongs the overall survival of patients, therefore, FOXM1 is considered a potential therapeutic target in ovarian cancer." (PMID 36505747, 2022). "Investigations of FOXM1 also showed that it plays a role in PARPi and paclitaxel resistance in ovarian cancer." (PMID 36505747, 2022). "FOXM1 shows potential as a new therapeutic target in ovarian cancer, where inhibition of FOXM1 is expected to reverse or delay platinum resistance, thereby prolonging PFS and overall survival (OS) in patients." (PMID 36505747, 2022). "Thiostrepton, a small molecule inhibitor (SMI) of FOXM1, reportedly sensitizes ovarian cancer cells to platinum-based chemotherapy." (PMID 36505747, 2022). "Through transcriptome sequencing analysis, RA methyl ester accelerated apoptosis in DDP resistant ovarian cancer cell line through inhibitory of Forkhead box M1 (FOXM1)." (PMID 36291619, 2022). "Our group report that Cyclin F and KIF20A are transcriptionally upregulated by FOXM1 in ovarian cancer." (PMID 35680842, 2022). "In conclusion, HO-ADSC exosomes promote the growth and metastasis of ovarian cancer cells in vivo by regulating FOXM1 signaling." (PMID 36359787, 2022). "FOXM1 expression is increased in cisplatin-resistant ovarian cancer cells, and inhibition of FOXM1 expression sensitizes cisplatin-resistant ovarian cancer cells." (PMID 36505747, 2022). "MFAP2 promotes cell proliferation and glycolysis by modulating the FOXM1/β-catenin signaling pathway in ovarian cancer." (PMID 36530974, 2022). "FOXM1 has been reported to confer resistance to chemotherapeutic agents such as platinum drugs in epithelial ovarian cancer." (PMID 35267428, 2022). "This study adds myeloma to a group of solid neoplasms including ovarian cancer and pancreatic cancer for which FOXM1-driven reprogramming of glucose metabolism and promotion of the Warburg effect have been well documented." (PMID 35794249, 2022). "Recent reports and our previous studies have shown that FOXM1 is an oncogene that plays a role in ovarian cancer growth and metastasis." (PMID 36359787, 2022). "Currently, drug therapy remains the mainstay of ovarian cancer treatment, and the need to identify new targets and more effective drugs against FOXM1 in order to improve treatment has been recognized." (PMID 36505747, 2022).
ovarian carcinoma (continued). "Compound XST-20 was identified to effectively suppress FOXM1 transcriptional activities and inhibit ovarian cancer cell proliferation." (PMID 35680842, 2022). "Among the seven compounds selected, DZY-3 and DZY-4 showed the best affinity for FOXM1 and the best inhibitory activity against two ovarian cancer cell lines, SKOV3 and A2780." (PMID 36505747, 2022). "Forkhead box M1 (FOXM1) has been reported to be involved in a variety of malignant behaviors of ovarian cancer cells, including growth, proliferation, invasion, and metastasis." (PMID 35965522, 2022). "Other studies have shown that FOXM1 enhances the invasion and metastasis of ovarian cancer cells by upgrading the expression of matrix metalloproteinase (MMP-2) and degrading the extracellular matrix." (PMID 36505747, 2022). "Circ_0061140 interference inhibited cell growth and metastasis via regulating the miR-370/FOXM1 axis in ovarian cancer." (PMID 35379058, 2022). "For example, it was revealed that forkhead box M1 (FOXM1) regulated cell proliferation, invasion and metastasis, chemo-resistance, and finally promoted poor prognosis in ovarian cancer patients." (PMID 35754835, 2022). "In conclusion, circular PVT1 increased FOXM1 level via binding to miR-149-5p and thus affected ovarian cancer cell viability, apoptosis and drug resistance." (PMID 33391456, 2021). "A key molecular alteration in ovarian cancer is the aberrant overexpression and activation of the transcription factor forkhead box M1 (FOXM1)." (PMID 34205406, 2021). "Integrated genomics analysis indicates that FOXM1 transcription factor network is significantly altered in 87% of cases of ovarian cancer." (PMID 35052372, 2021). "Our data have shown a new pathway circular PVT1 affected ovarian cancer cell viability and metastasis via miR-134-5p/FOXM1, thus providing a hint of uncovering novel countermeasure for ovarian cancer." (PMID 33391456, 2021). "As for DLX1, it has been suggested as an important target of FOXM1 to enhance the aggressiveness of ovarian cancer." (PMID 33740948, 2021). "The scope of the literature examining the function of FOXM1 using in vivo ovarian cancer models is currently limited." (PMID 34205406, 2021). "Altogether, these results indicated that FOXM1 was a key executor in DDX23-induced malignant phenotype of ovarian cancer." (PMID 34966670, 2021). "Further elucidations of DUBs that target FOXM1 in ovarian cancer are an important area for future investigations." (PMID 34205406, 2021). "The recent development of mouse models that recapitulate TME observed in human ovarian cancer provides a ripe opportunity to study the role of FOXM1 in the ovarian cancer TME." (PMID 34205406, 2021). "Several studies have reported that the FOXM1 small molecule inhibitor (SMI) thiostrepton sensitizes ovarian cancer cells to platinum-based chemotherapy." (PMID 34205406, 2021). "Rescue assays indicated that FOXM1 was a key executor in DDX23-induced malignant phenotype of ovarian cancer." (PMID 34966670, 2021). "Since ovarian cancers ultimately develop resistance to most chemotherapy, it is worthwhile to develop both indirect and direct FOXM1 inhibitors in parallel." (PMID 34205406, 2021). "In conclusion, circular PVT1 increased FOXM1 level via binding to miR-149-5p and thus affected ovarian cancer cell viability and migration." (PMID 33391456, 2021). "Forkhead Box M1 (FOXM1) expression in ovarian cancer exhibited high level when compared with normal tissues, and had relation with relatively poor survival." (PMID 33391456, 2021). "Additional studies have demonstrated that FOXM1 promotes ovarian cancer cell migration and invasion." (PMID 34205406, 2021). "There is strong rationale for targeting FOXM1 in cancer, particularly in aggressive cancers with poor survival outcomes such as ovarian cancer." (PMID 34205406, 2021).
ovarian carcinoma (continued). "Overexpression and activation of FOXM1 is frequent in high-grade serous carcinoma (HGSC), the most common and lethal form of human ovarian cancer, and is linked to copy number gains at chromosome 12p13.33." (PMID 33890574, 2021). "Here, the tissue model was used to investigate the potency of FOXM1 inhibition in ovarian cancer specimens, as the transcription factor network is altered in 87% of ovarian cancer patients." (PMID 33668819, 2021). "In this review, we first discuss the molecular mechanisms controlling FOXM1 expression and activity, with a specific emphasis on ovarian cancer." (PMID 34205406, 2021). "Integrated genomic analyses of ovarian carcinoma from TCGA Research Network reported that the FOXM1 transcription factor network changed significantly in 87% of ovarian cancer cases." (PMID 34966670, 2021). "Here, our findings identified the function and mechanism of circPVT1 and FOXM1 involved in ovarian cancer, indicating circular PVT1-mediated regulation of cell apoptosis and metastasis by way of targeting miR-149-5p axis." (PMID 33391456, 2021). "Several oncogenic transcription factors have been noted to promote FOXM1 overexpression in ovarian cancer." (PMID 34205406, 2021). "In ovarian cancer cell line SKOV3, KRT5 and KRT7 were upregulated by Forkhead box M1 (FOXM1) and KRT5 and KRT7 deficiency prevented migration." (PMID 34070214, 2021). "High expression of DDX23 was involved in the malignant proliferation and aggressiveness of ovarian cancer cells by regulating FOXM1 mRNA processing." (PMID 34966670, 2021). "Taken together, these data implicate FOXM1 in promoting chemoresistance, particularly to platinum-based drugs, in ovarian cancer." (PMID 34205406, 2021). "Our data revealed that FOXM1 expression level was raised in ovarian cancer and interlinked to the degree of malignancy and poor survival of patients with ovarian cancer." (PMID 33391456, 2021). "Ovarian cancer patients with high-expressed FOXM1 presented worse survival than those with low-expressed FOXM1." (PMID 33391456, 2021). "FOXM1 expression is elevated in multiple stages of ovarian cancer, from initial neoplastic transformation to late-stage metastatic spread." (PMID 34205406, 2021). "In a bioinformatic study analyzing FOXM1 isoforms enriched in 12 ovarian cancer tissues compared to 18 normal control tissues, two novel FOXM1 isoforms missing the NRD were identified within the top 5% enriched isoform genes." (PMID 34205406, 2021). "Taken together, these studies suggest that FOXM1 regulates the expression of key adhesion molecules and promotes their expression in contexts favorable to ovarian cancer progression." (PMID 34205406, 2021). "In agreement, inhibiting T-Like Cell-Originated Protein Kinase (TOPK), which is a protein in the MAPK/ERK pathway that also modulates the PI3K/AKT pathway, leads to decreased FOXM1 gene expression in ovarian cancer cells." (PMID 34205406, 2021). "FOXM1 is a transcription factor which is a key regulator of different oncogenic signaling pathways and is frequently upregulated in ovarian cancer." (PMID 33668819, 2021). "Taken together, these data suggest that altered amino acid metabolism in ovarian cancer cells upregulates FOXM1, which alters glycolysis and mitochondrial respiration by promoting aerobic glycolysis." (PMID 34205406, 2021). "Taken together, these data indicate that ncRNA alterations play a key role in promoting FOXM1 expression in cancer, including ovarian cancer, and that FOXM1 itself can function in miRNA dysregulation." (PMID 34205406, 2021). "A study using clinical samples suggested that the GRB7/extracellular signal-regulated kinases (ERK)/forkhead box M1 (FOXM1) signaling cascade is a promising molecular therapeutic target for ovarian cancer." (PMID 34783299, 2021). "Investigations of FOXM1 also support that there is a role with respect to PARPi and taxane resistance in ovarian cancer." (PMID 34205406, 2021).
ovarian carcinoma (continued). "Based on data from TCGA and CPTAC, we found that FOXM1 was upregulated in ovarian cancer at both mRNA and protein levels." (PMID 34966670, 2021). "In this review article, we address the current knowledge regarding the mechanisms of regulation and oncogenic functions of FOXM1, particularly in the context of ovarian cancer." (PMID 34205406, 2021). "FOXM1 was previously reported that it correlates with chemoresistance in cancer cells and patients and is upregulated in ovarian cancer cells after cisplatin treatment, and its overexpression in some cancers contributes to paclitaxel resistance." (PMID 33255409, 2020). "Treatment of ovarian cancer cells with RAME effectively inhibited the binding of FOXM1 to its target gene promoters by decreasing the FOXM1 expression." (PMID 33053721, 2020). "Further, the extract activated AMP-activated protein kinase (AMPK) and inhibited the mTOR/p70S6K and/or the AKT/ERK/FOXM1 (Forkhead Box M1) signaling cascade in ovarian cancer." (PMID 32726914, 2020). "This protein is involved in regulating the splicing events of FOXM1 in ovary and its elevated expression was reported in ovarian cancer." (PMID 33680951, 2020). "Treatment of ovarian cancer cells with RAME decreased the mRNA expression of FOXM1 target genes and the binding of FOXM1 to its target genes." (PMID 33053721, 2020). "Consistent with the data obtained in this study, other groups have determined that RA can reduce the expression of FOXM1 in neuroblastoma and in ovarian cancer cells." (PMID 30978209, 2019). "The transcription factor FOXM1 is frequently overexpressed in ovarian cancer and recent data suggest a possible role for its deregulated expression at the level of the cancer stem cell population." (PMID 29389895, 2018). "A recent study based on the analysis of 158 ovarian cancer patients indicates that overexpression of FOXM1 predicts poor prognosis, promotes the expression of VEGF-A, stimulates cell proliferation, migration and tissue invasion." (PMID 29389895, 2018). "Appropriately, FOXM1 overexpression in ovarian cancer correlates with poor patient survival and contributes to the development of paclitaxel resistance." (PMID 29180117, 2018). "In this study, we show using a large cohort of Middle Eastern ovarian cancer that co-expression of FoxM1 and β-catenin were significantly correlated with advanced stage." (PMID 29423068, 2018). "Our results emphasize the importance of FoxM1/β-catenin interaction in ovarian tumorigenesis and argue the importance of this pathway as a promising therapeutic target in high-grade ovarian cancer." (PMID 29423068, 2018). "In ovarian cancer, FOXM1 can also modulate cisplatin sensitivity by promoting the expression of the DNA damage-repair Exonuclease 1 (EXO1)." (PMID 29180117, 2018). "Recently, it has been shown that FoxM1 is involved in glucose metabolism of pancreatic or ovarian cancers." (PMID 29765517, 2018). "A recent study has documented 7-Difluoromethoxyl-5,4′-di-n-octyl genistein, a synthetic genistein analogue, attenuated ovarian cancer stem-like properties by downregulating FOXM1." (PMID 29743815, 2018). "Another recent study provided direct evidence that the FOXM1 overexpression confers highly malignant properties to ovarian cancer cells, consisting in EMT, stemness and chemoresistance." (PMID 29389895, 2018). "In previous studies, we observed that DFOG markedly suppressed tumor stemness and promoted ovarian cancer cell apoptosis by downregulating FOXM1 and inducing FOXO3a." (PMID 29088827, 2017). "We recently reported that DFOG suppresses cell growth and tumor stemness, and that it induces cell apoptosis by suppressing FOXM1 and upregulating FOXO3a in ovarian cancer." (PMID 29088827, 2017). "Next, we elucidated the clinical significance of OTUB1 and FOXM1 protein in 200 tissues of ovarian cancer." (PMID 27167337, 2016).